SIRT1 (sirtuin 1)
Diseases named in the same sentence as SIRT1 in open-access papers (continued):
Sharing a sentence is not in itself a finding about the gene and the disease.
breast cancer (continued). "In order to clarify the biological behavior of SIRT1 and evaluate its role in breast carcinoma, we evaluated SIRT1 expression patterns at the transcriptional and translational levels in human breast tumors and their corresponding normal breast tissues, according to St Gallen molecular subtype class." (PMID 29340027, 2017). "Reduced SIRT1 levels in HMLER breast cancer cells led to increased metastases in nude mice, and SIRT1 reduces the EMT in cancer and fibrosis by deacetylating Smad4 and repressing the effect of transforming growth factor-β signalling on matrix metalloproteinase-7 (MMP-7), a Smad4 target gene." (PMID 27793039, 2016). "A significant association was previously reported between the rs3758391 TT genotype and a higher mRNA expression of SIRT1 in healthy individuals, an observation which was only apparent in our normal controls but highly significant in breast cancer patients regarding serum SIRT1 level." (PMID 26999517, 2016). "Therefore, it would be of great value to study—in future investigations—the effect of the studied SNPs on SIRT1 gene and protein expression levels in breast cancer tissue." (PMID 26999517, 2016). "This indicates that SRT1720 promotes the pulmonary metastasis of breast cancer cells, while SIRT1 may be an important target for suppressing metastasis to the lung." (PMID 27793039, 2016). "Likewise, SIRT1 localizes to the promoter of sFRP1 and directly contributes to the aberrant epigenetic silencing of breast cancer cells." (PMID 27776347, 2016). "In this study, we constructed Sirt1 overexpressed MSCs (MSC-Sirt1) through infecting MSCs with an adenovirus containing the Sirt1 gene and used the 4T1 breast cancer cell line to observe the potential effect of MSC-Sirt1 on regulating breast cancer cells growth in vivo." (PMID 27782173, 2016). "The SIRT1 activator compound 1720 showed that lung metastasis was increased by implanted breast cancer cells, suggesting that SIRT1 could function, at least under certain circumstances, as a tumor-promoting factor." (PMID 27528025, 2016). "Furthermore, serum SIRT1 level in TT genotype carriers was significantly higher than in other genotype carriers in the breast cancer group." (PMID 26999517, 2016). "Firstly, SIRT1 up-regulation has been previously demonstrated in breast cancer." (PMID 26999517, 2016). "It is possible to predict that the observed elevation in serum SIRT1 level in breast cancer patients could be attributed to the up-regulation of SIRT1 gene expression." (PMID 26999517, 2016). "Interestingly, both genotypes exhibited, together, a significantly higher serum SIRT1 level compared with the AA genotype in the breast cancer group." (PMID 26999517, 2016). "Actually, several studies have indicated that overexpression of SIRT1 may correlate with poor prognosis in breast carcinoma." (PMID 26999517, 2016). "Altogether, our data suggest that SIRT1 may be included in the transduction network activated by estrogens through GPER toward the breast cancer progression." (PMID 26225773, 2015). "C-MYC also contributed to Sirt1 activation in breast cancer." (PMID 25815791, 2015). "Previous studies have demonstrated in colon cancer and breast cancer cells that SIRT1 localizes at the promoter of ECAD gene and its long-term inhibition via shRNA results in increased histone H4K16-and H3K9-acetylation respectively, which strongly associates with ECAD, TSG re-expression." (PMID 26622943, 2015). "In addition, we provide evidence regarding the involvement of SIRT1 in tumor growth stimulated by GPER ligands in breast cancer cells and xenograft models." (PMID 26225773, 2015). "SIRT1 knock-down or SIRT1 inhibitors (amurensin G and EX527) effectively suppressed the resistance to Hsp90 inhibitors (17-AAG and AUY922) in several MDR variants of human lymphoblastic leukemia and human breast cancer cell lines." (PMID 26416354, 2015).
breast cancer (continued). "However, the relationship between DBC1 and SIRT1 was been frequently dissociated as shown in breast cancer." (PMID 25823848, 2015). "Additionally, overexpression of SIRT1 with FOXO1 potentiated the transcription of multiresistance protein 2 (MRP2), and the basal activity and expression of SIRT1 was increased in tamoxifen-resistant breast cancer cells." (PMID 25569080, 2015). "Taken together, these findings suggested high SIRT1 may be breast cancer protective in a Notch1-depndent manner." (PMID 25420528, 2014). "Furthermore, we evaluated the prognostic value of SIRT1 and Notch1 signaling in patients with breast cancer." (PMID 25420528, 2014). "Possibly, combined inhibition of multiple histone-modifying enzymes, such as LSD1, HDAC2 and SIRT1, could lead to improved treatment of breast cancer patients." (PMID 25139823, 2014). "Our findings were in accordance with the observations that the negative association of SIRT1 with N1IC in breast cancer tissues." (PMID 25420528, 2014). "Therefore, we assessed the possibility of SIRT1 and components of the Notch1 signaling pathway as prognostic biomarkers for breast cancer." (PMID 25420528, 2014). "Notably, both breast cancer and hepatic cell carcinoma exhibit reduced SIRT1 levels compared with normal tissues." (PMID 25486244, 2014). "Additionally SIRT1 involvement has also been suggested in epigenetic silencing of DNA-hypermethylated tumor suppressor genes in breast cancer cells." (PMID 25424420, 2014). "While knockdown of SIRT1 had no major effect on IL-6 expression in breast cancer cells, ERα-driven control of the association of SIRT1 with chromatin contributes to SIRT1 activity in other contexts." (PMID 24771768, 2014). "To address whether the expression level of SIRT1and N1IC or combined expression status of SIRT1/N1IC was an independent prognostic factor in 122 patients with breast cancer, we performed multivariate survival analysis using two models." (PMID 25420528, 2014). "Previous studies have shown that modulating tissue NAD+ concentrations can influence the metastatic properties of breast cancer cells but whether this is mediated by SIRT1 (NAD+ is the co-substrate for SIRT1 catalysis) has yet to be investigated." (PMID 25380034, 2014). "Additionally, SIRT1 has been shown to suppress the EMT process in metastasizing breast cancer cells, and the development of fibrosis in organs following their implantation into nude mice." (PMID 25424420, 2014). "SIRT1 expression and Notch1 signaling have been implicated in tumorigenesis in many cancers, but their association with survival in breast cancer has not been determined." (PMID 25420528, 2014). "We introduced the MMTV-PyMT transgene into stocks of mice carrying the H355Y point mutation in the Sirt1 gene (an allele referred to as Sirt1Y that encodes a protein with no detectable catalytic activity) and studied the emergence of mammary tumors in Sirt1+/+, Sirt1+/Y, and Sirt1Y/Y females." (PMID 25380034, 2014). "The results showed that SIRT1-low/N1IC-high expression was associated with shorter OS and DFS compared with SIRT1-high/N1IC-low group, which further suggested an inverse correlation between SIRT1 and N1IC in breast cancer prognosis." (PMID 25420528, 2014). "In conclusion, this study has demonstrated that low expression of SIRT1 was significantly associated with poor outcome, and combined low expression of SIRT1 and high expression of N1IC could identify breast cancer patients with the worst prognosis." (PMID 25420528, 2014). "Recent studies in breast carcinoma have found SIRT1 to be an indicator of good prognosis." (PMID 25420528, 2014).
breast cancer (continued). "Similarly, miR-22 targets CDK6, SIRT1, and Sp1, which are genes involved in the senescence program, and induces cellular senescence in both human fibroblast and breast cancer cells." (PMID 24282530, 2013). "However, there is also a great deal of evidence showed that the expression of SIRT1 in breast cancer, ovarian carcinoma, bladder carcinoma, prostate carcinoma, and glioblastoma, is lower than that in normal tissues." (PMID 23805287, 2013). "Although DBC1 was first recognized as a tumor suppressor because it is deleted in breast cancer and principally inhibits SIRT1, recently there has been increasing evidence that DBC1 has an important role in the progression of human cancers via various cellular pathways." (PMID 24019980, 2013). "Inhibition of SIRT1 deacetylase activity has been reported to suppress ERα transcription whereas another report showed that SIRT1 repressed estrogen signaling and ERα-mediated cell growth in breast cancer cells in vitro." (PMID 24278473, 2013). "In addition, co-expression of DBC1 and SIRT1 in human cancers is becoming a more common phenomenon, as presented in hepatocellular carcinoma, gastric carcinoma, and breast carcinoma." (PMID 24019980, 2013). "However, high SIRT1 expression was reported to connect to poor survival in diffuse large B-cell lymphoma, gastric carcinoma, and breast cancer." (PMID 23272146, 2012). "These new mechanistic insights may also aid in understanding the role of SirT1 in breast cancer as well as in other organs in which local IGF-1 plays an important role." (PMID 17201918, 2007). "SirT1 is therefore a candidate target for chemoprevention against breast cancer." (PMID 17201918, 2007). "However, we tested the effects of SIRT1 on a series of colon and breast cancer phenotypic characteristics that would be predicted to change dramatically with re-expression of the TSGs under study." (PMID 16596166, 2006). "This study aimed to evaluate the interrelationship among silent information regulator (SIRT1), Forkhead box O3a (FoxO3a), and microRNA-34a (miR-34a), the latter of which promotes apoptosis by suppressing the proliferation, migration, and invasion of breast cancer cells." (PMID 41816745, 2025). "In early-stage breast cancer, SIRT1 may protect cells by keeping their DNA stable." (PMID 41300302, 2025). "Also, in breast cancer, there is an overexpression of SIRT1 and SIRT6." (PMID 40214422, 2025). "Inhibition of SIRT1 has been shown to reduce estrogen-induced cell growth and tumor development, indicating that combining SIRT1 inhibitors with antiestrogen therapies could offer more effective treatment strategies for HR+ breast cancer." (PMID 41300302, 2025). "Consequently, SIRT1 activation supports estrogen-induced breast cancer growth and survival." (PMID 41300302, 2025). "Recent studies have shown that reduced SIRT1 expression generates a secretome composing excess exosomes with unique cargo and soluble hydrolases that degrade the extracellular matrix, thereby promoting processes that increase breast cancer cell survival and invasion." (PMID 39596439, 2024). "Moreover, the influence of Neratinib on the cell senescence in AU565 cells was rescued by overexpressing SIRT1, implying that Neratinib might induce the cell senescence in mammary cancer cells by downregulating SIRT1." (PMID 38829772, 2024). "Moreover, it has been demonstrated that SIRT1 is involved in DNA damage response, genome stability, and tumor suppression in many other types of cancers in humans, including oral squamous cell carcinoma, ovarian cancers, and breast cancer." (PMID 37627400, 2023).
breast cancer (continued). "Furthermore, miR-211-5p could serve as a potential therapeutic target via targeting SETBP1 or SIRT1 for breast cancer." (PMID 34151707, 2021). "Interestingly, human BRCA1-associated breast cancers have been shown to have lower levels of SIRT1 than their normal controls, an effect likely caused via the transcriptional effects of BRCA1 on SIRT1 expression." (PMID 34750509, 2021). "Furthermore, while SIRT1 inhibition has been shown to lead to growth arrest and apoptosis in lymphoma and breast cancer, other studies indicate that SIRT1 may act as a tumor suppressor." (PMID 34907162, 2021). "Glutamine metabolism affected histone modifications in human breast cancer cell lines, and the treatment of non-invasive epitelial and invasive mesenchymal breast cancer cell lines with a glutaminase inhibitor induce a downregulation of epigenetic regulatory genes, such as Sirt1." (PMID 34026764, 2021). "However, a few studies have suggested that SIRT1 may act as a tumor activator in various human cancers, including breast cancer, prostate cancer, or ovarian cancer 38,39." (PMID 32398958, 2020). "Another report demonstrated that inhibition of SIRT1 reduced aromatase mRNA and protein levels in estrogen receptor negative (ER−) breast cancer cells possibly due to loss of ERRα binding to the aromatase promoter and subsequent inhibition of aromatase transcription." (PMID 33330467, 2020). "Moreover, targeting NNMT or downstream SIRT1 may represent a new therapeutic approach to improve the efficacy of breast cancer chemotherapy." (PMID 31101119, 2019). "Therefore, we hypothesized that NNMT promotes the ADM and PTX resistance in breast cancer by increasing the SIRT1 stabilization and activity." (PMID 31101119, 2019). "In order to determine whether HDAC SIRT1 interacts with histone H3 acetylated epi-marks in human breast cancer, we began by performing chromatin immunoprecipitation (ChIP) assays of SIRT1 on 50 breast tumors and their 50 matched normal tissues (n = 10 tumors for each of the 5 molecular subtypes)." (PMID 30093977, 2018). "Therefore, SIRT1 seems to be directly responsible for the modulation of H3k4ac, as well as H3k9ac and H4k16ac expression patterns, obviously through direct deacetylation, in breast cancer." (PMID 30093977, 2018). "Taken together, our findings indicated that lncRNA could regulate the progression and chemoresistance of breast cancer via modulating the expression levels of miR-4766-5p and SIRT1, which may have a pivotal role in breast cancer treatment and prognosis prediction." (PMID 29752439, 2018). "Interestingly, EMT-type CSCs (CD44+) are associated with low SIRT7 and share similar set of genes with OCT3/4, suggesting differential roles of Sirtuins on breast cancer stemness: SIRT1 is related to MET-type CSCs (ALDH1+), whereas SIRT7 is correlated with EMT-type (CD44+)." (PMID 30038266, 2018). "In addition, SIRT1 reduces drug-resistance in breast cancer." (PMID 30380732, 2018). "However, a slight increase of H3k4ac and H3k9ac expression on EZH2 promoter was also observed in the in (ER+) cell lines, implying that EZH2 expression could be regulated in part by SIRT1 in different subtypes of breast cancer." (PMID 30093977, 2018). "We wanted to investigate whether SIRT1 gene silencing could specifically alter the enrichment patterns of histone H3 acetylated epi-marks on the promoters of our target genes, and consequently, impact the targeted genes expression patterns in breast cancer." (PMID 30093977, 2018). "In addition, researches on SIRT1 in breast cancer were particularly confusing." (PMID 29752439, 2018). "They postulated that SIRT1 may be a co-activator of ER-α in breast cancer." (PMID 30380732, 2018). "Therefore, our study appears to support a tumor promoter role for SIRT1 in breast cancer." (PMID 29752439, 2018).
breast cancer (continued). "We also determined whether lncRNA-PRLB regulated SIRT1 expression in breast cancer cells." (PMID 29752439, 2018). "However, they only could show in an MCF-7 cell line (Breast cancer cells) that the reduction of Sirt1 involved reduced PGC1α and, subsequently, reduced NRF2 and enhanced susceptibility to oxidative stress." (PMID 29121859, 2017). "We conclude that SIRT1 may serve as a prognostic biomarker in breast cancer carcinomas." (PMID 29340027, 2017). "In addition, Sirt1 binds to all subtypes of the Dishevelled protein family in a number of different cell lines, such as human embryonic kidney cell lines, colon cancer cell lines, and breast cancer cell lines." (PMID 29073244, 2017). "In addition, human breast cancer cell treatment with nicotinamide induces cellular apoptosis in vivo through Sirt1 inhibition, although a recent study points to the fact that nicotinamide addition to cells can stimulate sirtuins due to rapid in vivo conversion of nicotinamide to NAD+." (PMID 29253849, 2017). "However, no studies exist, so far, on the role of SIRT1 gene polymorphism in breast cancer risk or prognosis." (PMID 26999517, 2016). "So far, no studies exist on the involvement of SIRT1 gene polymorphism in breast cancer." (PMID 26999517, 2016). "However, silibinin could have completely the opposite action in regulating SIRT1 expression in normal cardiac myocytes and breast cancer MCF-7 cells, where it downragulates SIRT1 and promotes apoptosis." (PMID 26785346, 2015). "Over-expression of SIRT1 in mouse embryo fibroblasts and articular chondrocytes has been reported to inhibit senescence, whereas reduced SIRT1 activity has been shown to induce senescence in human breast cancer MCF-7 cells, endothelial cells and articular chondrocytes." (PMID 25855056, 2015). "Therefore, we speculated that manipulation of miR-34a-SIRT1 axis may interfere with the oncogenic properties of breast cancer cells." (PMID 25826085, 2015). "One explanation for this hTERT down-regulation, which could account for growth inhibition in the breast cancer cells, could be due to a decrease in the downstream target of SIRT1, FOXO3a and c-MYC, which has been shown to increase hTERT expression in a SIRT1-dependent manner." (PMID 26459286, 2015). "However, dissection of these mechanisms of action is complicated by physical and functional interactions between ERα and SIRT1, where: (i) ERα is a SIRT1 substrate, and (ii) SIRT1 functions as an ER coregulator required for the oncogenic effects of estrogens in breast cancer." (PMID 24771768, 2014). "Therefore we believed that low expression of SIRT1 identifies a group of tumors with a very poor prognosis, and suggests that SIRT1 may be a potential therapeutic target in breast cancer." (PMID 25420528, 2014). "Conversely, SIRT1 overexpression antagonizes oncogene-induced cellular senescence in human diploid fibroblasts, and inhibition of SIRT1 by sirtinol has been shown to induce senescence-like cell growth arrest in human breast cancer MCF7 and human lung adenocarcinoma H1299 cells." (PMID 25070626, 2014). "However, despite increasing interest in SIRT1 and Notch1 signaling, their expression patterns and prognostic significance in breast carcinoma are unknown." (PMID 25420528, 2014). "However, in contrast to our results and other previous reports, some studies have indicated that over-expression of SIRT1 may correlate with poor prognosis in certain types of tumor, including breast carcinoma." (PMID 25420528, 2014). "This suggests that transcriptional changes for SIRT1 may not be implicated in breast cancer pathogenesis." (PMID 17003781, 2006). "SIRT1 Inhibitors: Compounds like cambinol have shown efficacy in reducing cancer stem cell populations and blocking EMT in breast cancer cells." (PMID 41300302, 2025).